KLF4 (KLF transcription factor 4)
Description:
Transcription factor; can act both as activator and as repressor. Binds the 5'-CACCC-3' core sequence. Binds to the promoter region of its own gene and can activate its own transcription. Regulates the expression of key transcription factors during embryonic development. Plays an important role in maintaining embryonic stem cells, and in preventing their differentiation. Required for establishing the barrier function of the skin and for postnatal maturation and maintenance of the ocular surface. Involved in the differentiation of epithelial cells and may also function in skeletal and kidney development.
Synonyms: EZF; GKLF
Tractability: PROTAC: UniProt records ubiquitination sites on it; ubiquitination databases record sites on it.
Gene: Protein-coding gene on chromosome 9 (107,484,852 to 107,490,482, reverse strand). Ensembl gene ENSG00000136826.
Subcellular location: Nucleus; Cytoplasm
Subcellular location (Human Protein Atlas): Nucleoplasm; Cytosol; Microtubules
Pathways (Reactome):
Developmental Biology: Transcriptional regulation of pluripotent stem cells; Transcriptional regulation of white adipocyte differentiation
Cell-Cell communication: Positive Regulation of CDH1 Gene Transcription
Gene expression (Transcription): FOXO-mediated transcription of cell cycle genes
Metabolism of proteins: Synthesis, secretion, and deacylation of Ghrelin
Gene Ontology:
Molecular function: DNA-binding transcription activator activity, RNA polymerase II-specific; DNA-binding transcription factor activity; promoter-specific chromatin binding; protein binding; RNA polymerase II cis-regulatory region sequence-specific DNA binding; RNA polymerase II-specific DNA-binding transcription factor binding; sequence-specific double-stranded DNA binding; DNA-binding transcription factor activity, RNA polymerase II-specific; transcription cis-regulatory region binding; zinc ion binding; beta-catenin binding; chromatin DNA binding; double-stranded DNA binding; histone deacetylase binding; lncRNA binding; phosphatidylinositol 3-kinase regulator activity; sequence-specific DNA binding; transcription coregulator binding
Biological process: cellular response to growth factor stimulus; cellular response to laminar fluid shear stress; defense response to tumor cell; negative regulation of angiogenesis; negative regulation of canonical NF-kappaB signal transduction; negative regulation of cell migration involved in sprouting angiogenesis; negative regulation of chemokine (C-X-C motif) ligand 2 production; negative regulation of DNA-templated transcription; negative regulation of extrinsic apoptotic signaling pathway in absence of ligand; negative regulation of G1/S transition of mitotic cell cycle; negative regulation of gene expression; negative regulation of heterotypic cell-cell adhesion; negative regulation of interleukin-8 production; negative regulation of leukocyte adhesion to arterial endothelial cell; negative regulation of response to cytokine stimulus; negative regulation of transcription by RNA polymerase II; positive regulation of DNA-templated transcription; positive regulation of gene expression; positive regulation of hemoglobin biosynthetic process; positive regulation of miRNA transcription; positive regulation of nitric oxide biosynthetic process; positive regulation of protein metabolic process; positive regulation of sprouting angiogenesis; positive regulation of telomere maintenance; positive regulation of transcription by RNA polymerase II; and 21 more
Cellular component: chromatin; cytoplasm; nucleoplasm; nucleus; euchromatin; transcription regulator complex
Genetic constraint (gnomAD): Loss-of-function variants: 14 observed, 31.35 expected, observed/expected ratio (o/e) 0.45, 90% interval 0.29 to 0.7. The synonymous counts are far from expectation, so gnomAD's model fits this gene poorly and the ratio says little. Missense variants: 737 observed, 617.07 expected, observed/expected ratio (o/e) 1.19, 90% interval 1.12 to 1.27. Synonymous variants: 398 observed, 279.98 expected, observed/expected ratio (o/e) 1.42, 90% interval 1.31 to 1.54.
Cancer hallmarks: cell replicative immortality (promotes); escaping programmed cell death (suppresses); proliferative signalling (promotes); invasion and metastasis (promotes); suppression of growth (promotes); invasion and metastasis (suppresses)
Homologues: Orthologues: chimpanzee KLF4 (100% identical), pig KLF4 (94% identical), rat Klf4 (92% identical), mouse Klf4 (91% identical), dog KLF4 (90% identical), guinea pig KLF4 (87% identical), macaque KLF4 (87% identical), tropical clawed frog klf4 (54% identical), zebrafish klf4 (35% identical), Drosophila melanogaster luna (19% identical). Paralogues in human: KLF2 (35% identical), KLF1 (26% identical), KLF5 (23% identical), KLF15 (21% identical), KLF3 (20% identical), KLF7 (20% identical), KLF8 (20% identical), KLF12 (20% identical), KLF6 (20% identical), SP8 (18% identical), KLF11 (17% identical), KLF10 (17% identical), and 10 more.
Diseases named in the same sentence as KLF4 in open-access papers:
KLF4 is named in the same sentence as 408 diseases in open-access papers, as found by Europe PMC text mining. Sharing a sentence is not in itself a finding about the gene and the disease. The quoted sentences say what the papers report.
breast cancer (260 papers, 2007 to 2026). A primary or metastatic malignant neoplasm involving the breast. "KLF4 deficiency in MDSCs markedly reduces pulmonary metastasis of breast cancer and melanoma, which correlates with decreased numbers of MDSC‐derived fibrocyte‐like cells and myofibroblasts." (PMID 41532367, 2026). "KFL4’s oncogenic potential is also linked to its metabolic regulation in breast cancer, which usually has high KLF4 expression." (PMID 40552304, 2025). "The increased nuclear expression of KLF4 has been associated with the aggressiveness of breast cancer phenotypes." (PMID 40616161, 2025). "ECM-mediated changes in the expression and/or cellular localization of SOX2, OCT4 and KLF4 are associated with prostate and breast cancer." (PMID 39611488, 2025). "Overexpression of wild-type KLF4 is tumorigenic, and methylation-incompetent mutated KLF4 was unable to initiate tumorigenesis in a breast cancer xenograft model, highlighting the importance of the methyl-inactivated degron for the oncogenic function of KLF4." (PMID 36639369, 2023). "In order to find out the possible reason underlying hypermethylation of KLF4 promoter in breast cancer, we detected the expression of DNMT1 in these 50 breast carcinoma and adjacent normal tissues by IHC analysis." (PMID 34150611, 2021). "In this study, we showed that the KLF4 expression was downregulated in human breast cancer tissues, which was associated with hypermethylation of its promoter region." (PMID 34150611, 2021). "Depletion of KLF4 by RNA interference or interference with PARP1 function by KLF4YYR/AAA (a PARylation‐deficient mutant) significantly sensitizes breast cancer cells to PARP inhibitors." (PMID 33231937, 2020). "A positive control interaction linking a distal breast cancer-associated locus with KLF4 demonstrated the strongest interaction with the KLF4 promoter region in both cell types." (PMID 32366252, 2020). "In light of the controversial functions reported for KLF4 in breast cancer, we confirmed that it inhibits several phenotypes associated with aggressive disease including proliferation, invasion, and migration." (PMID 32552913, 2020). "Bmi1 expression was also associated with favorable overall survival in a sample of 960 breast cancer patients, and high Klf4 expression was reported to be associated with longer disease-free survival and overall survival of breast cancer patients." (PMID 28422735, 2017). "Previous study has elucidated that the deficiency of KLF4, as an oncogene, inhibited breast cancer pulmonary metastasis in mice." (PMID 29254226, 2017). "For example, KLF4 expression and nuclear localization has been found associated with an aggressive phenotype in early breast cancer and part of a stem cell-like signature in poorly differentiated aggressive human tumors." (PMID 28412746, 2017). "Specificity of qPCR primers recognizing KLF4(FL) and KLF4α, respectively, as well as primers that detect both KLF4 variants (“KLF4 all”) allowed us to study breast cancer-associated KLF4 splicing in more detail." (PMID 27323810, 2016). "Since both KLF4 variants were detectable in most of the breast cancer samples, we wished to determine the KLF4α/KLF4(FL) ratio in each sample." (PMID 27323810, 2016). "Our reporter assays targeting the rs10816625/rs13294895 SNPs suggest that lower levels of expression of KLF4 are associated with increased breast cancer risk." (PMID 25652398, 2015). "In follow-up studies of breast cancer cases, these investigators found that small primary tumors having preferential nuclear localization of KLF4 correlated with an increased risk of death." (PMID 26109433, 2015).
breast cancer (continued). "In contrast, it has been recently shown that the loss of KLF4 negative regulation by the miR-7, in cancer stem-like cells (CSCs) derived from breast cancer, enhanced their metastatic capacity towards the brain." (PMID 25181544, 2014). "The outcome of early-stage breast cancer patients, defined as death by breast cancer, was linked to the immunohistochemical staining pattern of KLF4 in their primary tumor." (PMID 24429391, 2014). "Previous studies have shown that approximately 70% of human breast cancer has increased KLF4 expression and that up-regulated nuclear KLF4 expression is associated with a more aggressive phenotype." (PMID 21978458, 2011). "Earlier studies have however shown that 70% of breast cancers have elevated expression of Klf4 and that increased nuclear staining of Klf4 is associated with a more aggressive phenotype." (PMID 20514221, 2009). "This gene promotes breast cancer cell metastasis by deubiquitinating KLF4, and its mutation in primary tumour cells may suppress metastasis." (PMID 34507604, 2021). "In addition, higher levels of KLF4 in breast cancer are usually associated with a high risk of tumorigenesis and a poor prognosis." (PMID 33052880, 2020). "Accordingly, loss of KLF4 resulted in the induction of EMT programs in breast cancer cells." (PMID 32552913, 2020). "Impaired KLF4 or PARP1 has been previously linked to breast cancer formation." (PMID 33231937, 2020). "In this work, we have demonstrated that KLF4 is a pivotal causal factor for breast tumor initiation and invasion in both cultured cells and animal models; its abnormal accumulation tightly correlates with poor breast cancer prognosis." (PMID 33231937, 2020). "We hypothesized that the combination of GEN and SFN causes breast cancer inhibition in vitro and in vivo via inhibition of KLF4 post-translationally as well as HDAC2 and HDAC3, which acts in conjunction with KLF4." (PMID 29899271, 2018). "However, an in-depth study is warranted to study the association between KLF4 and E-cadherin expression in breast cancer cells." (PMID 29899271, 2018). "IL-1RA added to the coculturing system partially blocked the upregulation of tumor-associated pluripotency factors Sox2 and KLF4 in both breast cancer cells and ovarian cancer cells, which verified the role of IL-1β in the promotion of stem cell-like properties." (PMID 29670904, 2018). "Moreover, two new genetic variants in the estrogen-receptor positive breast cancer susceptibility locus 9q31.2 have been recently identified that target KLF4 via long-range chromatin interactions." (PMID 27323810, 2016). "Indeed, we find that PRMT5 upregulation tightly associated with an increase in KLF4 levels is a common feature in mammary cancer." (PMID 26420673, 2015). "Thus, increased levels of PRMT5 and KLF4 are highest in tissues from breast cancers associated with poor prognosis." (PMID 26420673, 2015). "KLF4 role switching in breast cancer may be associated with the stage and subtype of the disease as it has been implicated in promoting the progression of low-grade primary ductal carcinoma while suppressing highly aggressive triple-negative breast cancer (TNBC)." (PMID 39995670, 2025). "However, some studies have shown that KLF4 expression is associated with poor survival in breast cancer, prostate cancer, colorectal cancer, and skin squamous cell carcinoma, which indicates that KLF4 may be an oncogene." (PMID 35177016, 2022). "In HaCaT cells, there was a H3K27ac peak at the KLF4 promoter that interacted with several regions across the gene desert including psoriasis-associated enhancers 3 and 4 and at the previously published interacting region from the breast cancer study in both unstimulated and stimulated HaCaT cells." (PMID 32366252, 2020). "In contrast, in breast cancer cells, KLF4 acts as an oncogene and activation of KLF4 upregulates Laminin‐5 expression, which in turn facilitates tumor metastasis." (PMID 41532367, 2026).
breast cancer (continued). "In breast cancer cells, KLF4 functions as an oncogenic factor, upregulating CXCL5 and subsequently inducing GM‐CSF expression in the bone marrow." (PMID 41532367, 2026). "In survival analysis, breast cancer patients with elevated ANGPTL4 or KLF4 protein levels had poorer overall survival relative to those with low ANGPTL4 or KLF4 expression." (PMID 40616161, 2025). "We have previously demonstrated in a metastatic breast cancer model that KLF4 knockdown reduces granulocyte-macrophage colony-stimulating factor (GM-CSF), which is essential for MDSC development, through regulation of CXCL5, delaying tumor development." (PMID 40552304, 2025). "Reduced levels of m6 A modification in breast cancer stabilize KLF4 and NANOG mRNA, leading to the enrichment of stem cells and promoting tumorigenesis." (PMID 40382536, 2025). "In humans, six different KLF4 splicing isoforms are reported in breast cancer, including full-length KLF4 and five other intron-skipping isoforms." (PMID 40552304, 2025). "Specifically, ANGPTL4 and KLF4 were both highly expressed in metastatic breast cancer, and further co-expression analysis indicated that ANGPTL4 and KLF4 were simultaneously expressed in breast cancer tissue microarray (R = 0.3610, p = 0.0183, n = 44)." (PMID 40616161, 2025). "For example, exosome-mediated miR-10b secretion inhibits the protein levels of its target genes (HOXD10 and KLF4) and enhances breast cancer cell invasion." (PMID 39744442, 2025). "These regulatory mechanisms highlight the critical role of KLF4 in determining the biological behavior of breast cancer cells." (PMID 39995670, 2025). "Nonetheless, KLF4 is overexpressed in approximately 70% of primary breast ductal carcinomas, implicating its oncogenic role in breast cancer progression." (PMID 40616161, 2025). "One of the isoforms, KLF4α, which lacks the KLF4 exon 3 sequences, antagonizes the function of full-length KLF4 in breast cancer and pancreatic cancer." (PMID 40552304, 2025). "In cervical cancer, it has been reported as reduced, while in breast cancer, Klf4 expression was overexpressed." (PMID 38668382, 2024). "In breast cancer, the KLF4α/KLF4 (full length) (FL) ratio increased in tumors, leading to reduced expression of KLF4-L target genes and increased cell proliferation." (PMID 38539439, 2024). "By interacting with and sequestering KLF4-L in the cytoplasm, KLF4α or KLF4-S counteracted critical nuclear regulatory functions, thereby adding complexity to the role of KLF4 in breast cancer." (PMID 38539439, 2024). "NOTCH1 and JAG1 are upregulated in breast cancer by KLF4 and BMP4, which, in turn, influences CSC migration and spread." (PMID 39547513, 2024). "For example, KLF4 played a pro-tumor role in breast cancer maintenance, migration and invasion, while in gastrointestinal cancer it acted as a tumor suppressor by inhibiting tumor growth and metastasis." (PMID 37031197, 2023). "In contrast, knockdown of SIRT1 downregulated KLF4 and inhibited the stemness of breast cancer cells." (PMID 37031197, 2023). "KLF4 also functions as an oncogene to promote the proliferation of bladder cancer and breast cancer cells in the presence of RASV12-Cyclin-D1 signaling or the absence of P21." (PMID 37723138, 2023). "For instance, PRMT5-methylation of KLF4 and then retards its ubiquitination by pVHL and stabilizes KLF4, thereby enhancing oncogenic signaling in breast cancer." (PMID 36878903, 2023). "Regarding its commitment to tumor metabolic rewiring, in breast cancer, elevated KLF4 expression has been detected and contributes to activating phosphofructokinase (PFKP), a key enzyme involved in the glycolysis pathway." (PMID 37835497, 2023). "The expressed KLF4 protein positively regulates the formation of VM in triple-negative MDA-MB-231 breast cancer cells." (PMID 37762678, 2023).